ACSL3 (acyl-CoA synthetase long chain family member 3)
Diseases named in the same sentence as ACSL3 in open-access papers (continued):
Sharing a sentence is not in itself a finding about the gene and the disease.
tumor (continued). "Given that NF2 is a well-established tumor suppressor gene, we focused on subsequent analyses of INSIG1 and ACSL3." (PMID 41564380, 2026). "Stabilization of ACSL3 mRNA promotes ferroptosis in CRC cells, acting as a tumor-suppressive mechanism." (PMID 41288931, 2025). "In the RNAseq dataset, both ACSL3 and PHKG2 were expressed higher in the post-radiotherapy tumor tissues than in the pre-radiotherapy tumor tissues." (PMID 39169204, 2024). "In FAO, ACSL3 inhibition with enhanced MGF and ACADL regulating Hippo/YAP pathway are anti-tumor immunity strategies." (PMID 38841622, 2024). "The findings affirmed that ACSL3 and ACAT1 expressions were upregulated and downregulated, correspondingly in tumor tissues." (PMID 39323079, 2024). "qRT‐PCR results implied that ACSL3 and ACAT1 expressions were upregulated and downregulated, correspondingly in tumor tissues." (PMID 39323079, 2024). "As a result, ACAT1, ADH4 and ECI1 were even more down-regulated in HBV-positive HCC tumor tissue, and ACAT1, ADH4 and ACSL3 were down-regulated in HepG2.2.15 to a higher degree." (PMID 37957550, 2023). "In KRAS mutant NSCLC, FAO is facilitated by the upregulation of long-chain acyl-CoA synthetase 3 (ACSL3), the enzyme responsible for activating free FAs, allowing tumor cells to meet the increased ATP demand." (PMID 36675307, 2023). "In the clinical group Tumor status: Tumor free and with tumor, the genes TOP2A, BIRC5, VEGFA had highly statistical significance, while the genes HIF1A, ACSL3, FTH1 didn’t have statistical significance." (PMID 37248280, 2023). "ACSL3, EPAS1, FASN, GSTP1, LDHB, and NEDD4L were identified as the candidate genes through the intersection of tumor-related genes, DEGs, and ferroptosis-related genes." (PMID 35223835, 2022). "Furthermore, we found that knockdown of UBXD8, AP2A, or ACSL3 significantly suppressed sphere formation and xenograft growth, indicating that lipid droplet‐mediated Numb degradation is important for F. nucleatum‐mediated gain of stem‐like features and tumor progression." (PMID 35170250, 2022). "As discussed in this review, ACSLs such as ACSL3 and ACSL4 have a double-edged effect, that is, they have both anti-tumor as well as pro-tumor effects." (PMID 36497375, 2022). "The upregulated ACSL3, DDIT4, RRM2, and SLC2A1 with HR > 1 were considered as oncogenes, whereas the downregulated HERPUD1 and PEBP1 with HR < 1 were regarded as tumor suppressors." (PMID 34499810, 2021). "Four ferroptosis driver genes FLT3, ALOX12B, ALOX15, and VDAC2, had a low CNV, and four ferroptosis suppressor genes ACSL3, CISD1, FANCD2, and SLC3A2, had a high CNV, indicating that ferroptosis was inhibited in tumor development." (PMID 34434214, 2021). "Our in vivo results show that Acsl3 knockout hinders PDAC progression, markedly reduces tumor fibrosis and tumor-infiltrating immunosuppressive cells, and increases cytotoxic T cell infiltration." (PMID 33127675, 2020). "We showed that ACSL3 contributes to PDAC progression by driving the production and secretion of the profibrotic protein PAI-1 from tumor cells." (PMID 33127675, 2020). "The decreased tumor immunosuppression upon Acsl3 deletion was also recapitulated in KPCC;Acsl3−/− compared to KPCC;Acsl3+/+ mice." (PMID 33127675, 2020). "Cord blood from newborns (WBCs) DNA methylation of the ACSL3 promoter, Intragenic p19INK4α DNA methylation in adult blood (PBLs), CDH1, HIN1, PARPβ, and TWIST promoter DNA methylation in adult tumor tissue DNA methylation of the ESR1 promoter, BRCA1, CCND2, and DAPK." (PMID 40182693, 2025). "For example, the potential of exogenous MUFA to mitigate ferroptosis without affecting ACSL3, as well as the dynamic regulation of drug resistance by lipid supply in the tumour microenvironment, necessitate additional investigation." (PMID 41158124, 2025).
tumor (continued). "Significantly, ACSL3 and HADHA were upregulated in advanced tumor grade." (PMID 37540213, 2023). "ACSL3 has a favorable correlation with CTNNB1, a recognized tumor-promoting gene." (PMID 36338658, 2022). "To investigate how lipid droplet‐mediated Numb degradation influences F. nucleatum infection‐enhanced self‐renewal and tumor progression, we performed a sphere formation assay and xenograft assay in HCT116 and HT29 cells when UBXD8, AP2A, or ACSL3 was knocked down." (PMID 35170250, 2022). "Neither ACSL3 nor ACSL4 were detected on the surface of lipid droplets in either normal liver tissue or in non-HCC tumour cells in any of the samples examined." (PMID 32286604, 2020). "Moreover, qPCR from mouse tumor samples evidenced a decrease in Pai-1 mRNA in KPC;Acsl3−/− tumors compared to KPC;Acsl3+/+ tumors, additionally confirming our in vitro results." (PMID 33127675, 2020). "Furthermore, exploration of enzymes revealed that ACADSB (which was also highlighted by previous analyses), ACSL3, and ACSL4 regulate proteins that stimulate tumor cell proliferation, including p-AKT, LSD1, and β-catenin." (PMID 33424926, 2020). "Differences arise in the immediate outputs—glutaminolysis via SLC7A5 in NSCLC, fatty-acid activation via ACSL3 in CRC, and pro-migratory signaling via RAC3—and in whether CAFs act primarily by secreting a writer versus inducing tumor writers through growth-factor signaling." (PMID 41280938, 2025). "This could lead to overinterpretation of the role of genes like ACAT1 and ACSL3 without understanding the precise mechanisms by which they influence tumor behavior." (PMID 39323079, 2024). "Of ACSLs, ACSL5 was considered as the target gene, although lysoPCs may stimulate ACSL isoform activations and promote isoform‐specific biological processes, for example, ACSL1‐involved pro‐inflammation, ACSL3‐regulated androgen responsiveness or ACSL4‐and ACSL5‐related tumour suppression." (PMID 36639836, 2023). "Furthermore, it seems that tumor tissues have low expression of ACSL3, FDFT1, and HMGCR, and the high expression of ACSL3, FDFT1, and HMGCR patients was shown to be significantly associated with better OS and DFS, which indicated the suppression roles in carcinogenesis." (PMID 35322581, 2022). "Furthermore, ferroptosis-related genes with copy number amplification (including FADS2, NQO1, ABCC1, ACSF2, HMOX1, FANCD2 and SQLE) demonstrated higher expression in tumour tissues, and those with copy number deletion (including CRYAB, ACSL3, ZEB1) demonstrated lower expression in tumour tissues." (PMID 35145965, 2022).
infection (5 papers, 2013 to 2025). The state of being infected such as from the introduction of a foreign agent such as serum, vaccine, antigenic substance or organism. "Specifically, GAPDH1, IDH2, and FAS1b were significantly downregulated by infection in both dietary groups, while GlyS59, Acsl3, and HADH1 were significantly downregulated only in the NO group." (PMID 41390792, 2025). "Since knock-down of Acsl3 expression inhibits polio replication, it is impossible to directly examine the role of Acsl3 in activation of FA import upon infection." (PMID 23762027, 2013). "We also observed proteolytic cleavage of Acsl3 and FATP3 and loss of association of FATP3 with cellular structures upon infection, suggesting that modulation of acyl-CoA synthetase activity in infected cells is very specific." (PMID 23762027, 2013). "Infection with PV activated the import of long-chain FAs, which related to the upregulation of cellular long-chain acyl-CoA synthetase long-chain family member 3 (ACSL3) activity." (PMID 32973693, 2020). "In the present study, we analyzed different time points of infection and found that ACSL1, ACSL3, ACSL4, ACSL5 and ACSL6 were all recruited into the lumen of the Ct inclusion as early as 6 hpi and as late as 24 hpi." (PMID 26988341, 2016).
cardiovascular disease (1 paper, 2025). "In contrast, ACSL4, which exerts effects opposite to ACSL3 in ferroptosis, is considered a risk factor in cardiovascular disease." (PMID 41288931, 2025). "In addition to the roles of ACSL3 and ACSL4 in cardiovascular disease via the ferroptosis pathway, further investigation of alternative pathways may provide additional insights into the contributions of these targets to cardiovascular pathology." (PMID 41288931, 2025).
ACSL3 also shares sentences with these, for which no sentence is quoted: steatosis (4 papers); cholangiocarcinoma (3); type 2 diabetes (3); Alzheimer disease (2); metastatic disease (2); acute myeloid leukemia (1); allergic disease (1); bile duct cancer (1); Childhood Asthma (1); chronic pancreatitis (1); cyst (1); depression (1); eosinophilia (1); Fanconi anemia (1); Hepatic steatosis (1); hereditary spastic paraplegia (1); hyperreactivity (1); Hypertension (1); leiomyosarcoma (1); lymphoma (1); MALT lymphoma (1); metabolic disorders (1); metastatic cancer (1); oral squamous cell carcinoma (1); renal cell carcinoma (1); rhabdomyosarcoma (1); sarcoma (1); sarcopenia (1); soft tissue tumour (1); squamous cell carcinoma (1).
A further 2 diseases each share a sentence with ACSL3 in 1 paper.